RNA5S12 (RNA, 5S ribosomal 12)
Synonyms: RN5S12
Gene: Ribosomal RNA gene on chromosome 1 (228,634,871 to 228,634,989, reverse strand). Ensembl gene ENSG00000199270.
Gene Ontology:
Molecular function: structural constituent of ribosome
Cellular component: ribosome
Homologues: Orthologues: dog 5S_rRNA (100% identical), macaque 5S_rRNA (100% identical), rabbit 5S_rRNA (100% identical), chimpanzee 5S_rRNA (87% identical). Paralogues in human: RNA5S1 (100% identical), RNA5S10 (100% identical), RNA5S11 (100% identical), RNA5S13 (100% identical), RNA5S14 (100% identical), RNA5S15 (100% identical), RNA5S16 (100% identical), RNA5S17 (100% identical), RNA5S2 (100% identical), RNA5S3 (100% identical), RNA5S4 (100% identical), RNA5S5 (100% identical), and 26 more.